TPO (thyroid peroxidase)
Diseases named in the same sentence as TPO in open-access papers (continued):
Sharing a sentence is not in itself a finding about the gene and the disease.
thyroid (continued). "A humanized anti-TPO IgG1 antibody was effective in killing thyroid epiCsTPO in ADCC and CDC assays, whereas thyroid epiCsTPO,CD64t were fully protected." (PMID 36593395, 2023). "High levels of anti-thyroid peroxidase (Anti-TPO) and anti-thyroglobulin (Anti-TG) antibodies indicate that this thyroid disease occurs due to a disorder in the immune system." (PMID 36810529, 2023). "Main outcome measures included thyroid stimulating hormone (TSH), Free Thyroxine (FT4), and anti-thyroid peroxidase antibodies (TPOab) levels in serum, the prevalence of thyroid diseases and hyperprolactinemia." (PMID 37854182, 2023). "This case raises the clinical pearl that anti-thyroid antibodies, e.g anti-TPO antibody, can be seen in those with autoimmune encephalopathies other than HE and HE remains a diagnosis of exclusion." (PMID 36974252, 2023). "This study involved 62 DS patients, of which 48 had positive thyroid autoimmune markers (TPO-Ab and/or Tg-Ab) and were placed in the AITD group, while the remaining 14 were placed in the non-AITD group." (PMID 37234806, 2023). "Although anti-TPO Ab and anti-TG Ab were elevated in psoriasis and control subjects, there was no statistical significance when the two groups were compared based on thyroid auto-antibodies." (PMID 38192953, 2023). "Patients in the two groups were similar in terms of sex, age, underlying thyroid disease, pre-surgery weight and BMI, pre-surgery TSH and pre-surgery positive tests for Tg Ab or TPO Ab." (PMID 37074559, 2023). "For thyroid disease, a seroprevalence of 2.2% for TRAb (vs. 1% in HC), 0% for anti-TPO (vs. 2.5% in HC) and 4.3% for anti-Tg (vs. 3.5% in HC) was found for patients with CD." (PMID 37716983, 2023). "So, regular follow-ups with serial thyroid function tests to identify changes in thyroid hormone levels in patients with positive anti-TPO antibodies would ensure the early identification of thyroid disorders in these patients." (PMID 38289816, 2023). "We confirmed the elevated rates of pernicious anemia and thyroiditis by comparing the rate of positive tests for anti-gastric parietal cells and anti-TPO in the two groups." (PMID 37753082, 2023). "First, our study did not include essential information regarding iodine exposure levels, TPO antibody status with respect to thyroid disease, and histopathological findings." (PMID 38137904, 2023). "If a positive TPO Ab status would suggest a state of concurrent thyroiditis, a contrary point is that hampered thyroid peroxidase functioning would be expected to decrease RAI organification." (PMID 35687484, 2022). "In the study group of women with autoimmune diseases 47 out of 268 resulted positive for thyroiditis having positive the research for anti-TPO, anti-TG or both antibodies, showing a prevalence of 17.54%." (PMID 35222042, 2022). "The models were based on a small set of preselected thyroid-related risk factors, including free thyroxine (FT4), free triiodothyronine (FT3), autoantibodies to thyroid peroxidase (anti-TPO), as well as Body Mass Index (BMI), age and ethnicity." (PMID 35862421, 2022). "Of interest, treating NOD.H2h4 mice with blocking antibodies to PD-1 and to CTLA-4 markedly enhances thyroiditis and autoantibodies to thyroglobulin and TPO." (PMID 35572553, 2022). "Thyroid function tests were concerning for thyroiditis and anti-thyroid peroxidase antibodies were positive." (PMID 35733495, 2022). "In particular, the presence of thyroid antibodies against thyroglobulin (anti-TG), thyroid peroxidase (anti-TPO), or thyrotropin receptor autoantigens (anti-TR) are common pregnancy-related diseases." (PMID 35222042, 2022). "Eight patients with abnormal results of TSH or a history of thyroid disease were positive to at least one thyroid autoantibody (anti-TPO or anti-TG)." (PMID 35984815, 2022).
thyroid (continued). "Several studies have revealed the significant correlations between clinical thyroid-related antibodies like TPO-Ab and TR-Ab, and different bacterial abundances by Spearman’s correlation distance." (PMID 34867823, 2021). "Almost half of all women who develop postpartum thyroiditis and who have TPO antibodies will remain hypothyroid for their entire life." (PMID 34946265, 2021). "Approximately one in ten young women have anti-thyroid peroxidase (TPO) antibodies, and they are present in one in four euthyroid women who have a member of the family with thyroid disease." (PMID 34946265, 2021). "TSH levels were similar between these groups, as was the T3/T4 ratio and the presence of thyroid antibodies (anti-TPO and anti-Tg)." (PMID 34307412, 2021). "Eight (34.8%) patients were found to have abnormal thyroid functioning, including elevated thyroid peroxidase antibodies (17.4%), increased anti-thyroglobulin antibodies (13.0%), and increased total triiodothyronine and thyroxine (8.7%)." (PMID 34234736, 2021). "ID occurs often in thyroid diseases as well and deteriorates preexisting thyroid dysfunction, for example, through inhibiting the activity of heme dependent TPO." (PMID 34064075, 2021). "The mechanism of anti-thyroid agents is realized via action on inhibition of thyroid peroxidase (TPO) (Engler, Taurog & Nakashima, 1982; Wegner, Browne & Dix, 2016), the enzyme responsible for oxidation of iodide in the biosynthesis of thyroid hormones." (PMID 34141485, 2021). "Five out of the 12 were found to have positive thyroid antibodies (anti-TPO, anti-Tg and anti-TRAb)." (PMID 32163916, 2020). "Anti-TPO titers were assessed in cases with a maternal history of thyroid disease, either at diagnosis or early in the follow-up." (PMID 32765423, 2020). "Most patients with thyroiditis are usually positive for antibodies such as thyroid peroxidase (TPO) and/or thyroglobulin (Tg) antibodies." (PMID 33391917, 2020). "Anti-thyroid drugs are used to treat hyperthyroidism as they normalise thyroid function through binding to the thyroid peroxidase enzyme." (PMID 32027661, 2020). "From the sera of 150 patients withType-1 diabetic patients; The positivity of thyroid Anti TPO was 17.3% of patients while Anti TG was positive in 28% of patients and both tests was positive in (11.6%) of patients." (PMID 31372126, 2019). "In our study’s thyroiditis cohort, of the 49 patients tested for TPO/TG Ab, only 18 had positive titers." (PMID 30693099, 2019). "To confirm the euthyroid HT mouse model, we also analyzed the concentrations of Tg-Ab and TPO-Ab, thyroid function-related parameters in serum." (PMID 31729993, 2019). "In the total cohort, 11% had elevated thyroperoxidase antibodies (anti-TPO) and 5% had elevated transglutaminase antibodies, indicating thyroid and celiac disease, respectively." (PMID 31170007, 2019). "This is expected, since anti-Tg is a well-established marker in differentiated thyroid cancer (DTC) diagnosis and is considered a less specific marker in thyroid disease compared to anti-TPO." (PMID 31467701, 2019). "Anti-TPO antibodies are more common than anti-Tg antibodies and more indicative for thyroid disease and are detected in 90–95% of AITD patients, 80% of GD, and 10–15% of non-AITD patients." (PMID 31428301, 2019). "The spectrum of autoantigens reacting with the patient sera in cases of AITDs mainly involves three thyroid autoantigens: thyroglobulin (Tg), thyroid peroxidase (TPO), and TSH-R." (PMID 30881358, 2019). "The presence of thyroid anti-TPO antibodies were found positive in 40% of hypothyroid pregnant females in one of the epidemiological study, while another study reported 57.1% in subclinical hypothyroid cases." (PMID 31805890, 2019). "Next, we assessed the subcategories of ANA and anti-ENA autoantibodies found in thyroid-, anti-TPO-, and anti-Tg-positive subjects." (PMID 30911555, 2018).
thyroid (continued). "The prevalence of ANA which is the cornerstone marker in systemic autoimmune disease was found to be 20.4% in thyroid-positive subjects, 18.0% in anti-TPO-positive subjects, and 17.6% in anti-Tg-positive subjects." (PMID 30911555, 2018). "In two studies, thyroid disorders were diagnosed based on the presence of TPO-Abs, whereas an increased TSH value with a cut-off level of 4.0 or 4.5 mIU/L was used for diagnosis in the other two studies." (PMID 30249251, 2018). "The incidence was also reported to be 1.1% (15/1357) in patients with autonomous thyroid disease between 1 and 13 months after treatment, which increases ~10-fold when anti-TPO antibody levels are elevated before treatment." (PMID 29069397, 2018). "In fact, only 52% of patients with a positive history of thyroid disease have detectable anti-TPO/anti-Tg levels." (PMID 29675021, 2018). "In a previous study, anti-TPO Ab was detected in 67% of patients with painless thyroiditis after nivolumab therapy." (PMID 29884162, 2018). "Of the thyroid antibodies, anti-TPO alone played a significant role in predicting persistent disease of CSU." (PMID 30515422, 2018). "The prevalence of ANA was similar in subjects who were thyroid positive (20.5%), anti-TPO positive (18.1%), and anti-Tg positive (17.7%)." (PMID 30911555, 2018). "These were: polymyalgia, rheumatoid arthritis, seronegative-inflammatory arthritis, Crohn's disease, ulcerative colitis, and TPO-positive thyroiditis." (PMID 30190931, 2018). "Thyroid peroxidase (TPO), originally described as thyroid microsomal antigen, is a member of the thyroid autoantigens which includes thyroglobulin and thyroid-stimulating hormone receptor." (PMID 29915578, 2018). "Risk factors for the development of Alemtuzumab-induced GD were a family history of thyroid diseases, female sex, younger age, smoking habit, lower administered dose of the monoclonal Ab, and pretretment postivity for thyroid peroxidase (TPO) antibody (Ab)." (PMID 29033895, 2017). "Anti-TPO antibodies are more common than anti-Tg antibodies and more indicative for thyroid disease." (PMID 28536577, 2017). "Surprisingly, the beneficial action of anti-TPO antibody on breast cancer was restricted to women with thyroid volume (10–18 ml) in the normal range of between 10.7 and 17.5 ml." (PMID 28536577, 2017). "Eight subjects with LS were found among the 30 visited, 7 of whom were positive for anti-TPO antibodies, but only 4 had a thyroid disease." (PMID 28701998, 2017). "Diagnosis for Graves' disease, toxic nodular goiter, and postpartum thyroiditis was mostly clinical with only 20% of the patients able to afford thyroid autoantibody (thyroglobulin, thyroid peroxidase) testing." (PMID 28326101, 2017). "Qualitative and quantitative alterations in TPO activity, TPO messenger ribonucleic acid (mRNA), and protein expression can be related to thyroid changes and have been reported in pathological thyroid tissues." (PMID 26300979, 2015). "A total of three patients with anti-TPO antibody positivity had a family of autoimmune diseases (one thyroid and two diabetes mellitus)." (PMID 25653881, 2015). "The relationship between TPO expression and prognosis of thyroid disease has been determined in different studies." (PMID 26300979, 2015). "Anti-TG and anti-TPO positivity prevailed in females, while RF showed male predominance, in accordance with the observed clinical differences, and with the dominance of thyroiditis in women and polyarthritis in men." (PMID 24963499, 2014). "In women with positive thyroid peroxidase antibodies who recover from postpartum thyroiditis, there is a 70% recurrence rate in subsequent pregnancies." (PMID 24987536, 2014). "Significant gender differences were found for eight investigated factors, six of which were predominant in women (Raynaud's phenomenon, thyroiditis, anti-SS-B, anti-DNA, anti-TG, and anti-TPO) and two in men (polyarthritis, RF)." (PMID 24963499, 2014).
thyroid (continued). "Women with the presence of thyroid peroxidase antibodies in early pregnancy have 30 to 50% chance of developing postpartum thyroiditis." (PMID 24987536, 2014). "Thyroid antibodies can serve as useful clinical predictors of thyroid dysfunction, for example, TPO-Ab and post partum thyroiditis and TSHR-Abs and neonatal hyperthyroidism." (PMID 23691429, 2013). "Anti-TPO antibodies were found together with thyroid disorders in seven patients, with allergy in four and with asthma and rheumatoid arthritis in three." (PMID 23776613, 2013). "Since both TPO and Tg can initiate thyroiditis in animal models, this suggests that both are potent autoantigens." (PMID 23691429, 2013). "Other laboratory tests, such as detection of thyroid peroxidase antibodies or free T4 measurement using liquid chromatography/tandem mass spectrometry, can also provide useful information in identifying true thyroid abnormalities during pregnancy." (PMID 23762775, 2013). "Thyroid dysfunction was equally prevalent in women with GDM and normal pregnant women but 27% of them had positive titer of TPO Ab that warrants follow up for post-partum thyroiditis, dysfunction." (PMID 24353594, 2013). "In order to produce thyroid damage, the R26R;TPO-Cre mice were subjected to partial thyroidectomy (PTx) that was previously shown to serve as a model to study thyroid regeneration." (PMID 24278321, 2013). "Other studies have demonstrated a transient lithium induced increase in titres of thyroid auto-antibodies (thyroid peroxidase auto-antibodies) present prior to lithium administration." (PMID 23391071, 2013). "TPO antibodies, thyroiditis and serum T4 in Hi-expressor transgenics, Lo-expressor transgenics and WT mice." (PMID 22970131, 2012). "Considering thyroid function, 389 (29.9%) of mothers had a positive family history of thyroidal disease, while 165 (12.7%) and 87 (6.7%) women had elevated levels of anti-TPO and anti-TG antibodies, respectively." (PMID 22175032, 2011). "The patient had co-existing acetylcholine receptor-antibody positive myasthenia gravis (treated with pyridostigmine) and thyroglobulin and thyroid peroxidase antibody positive thyroiditis." (PMID 20825655, 2010). "Anti-TPO antibodies were elevated in patients 1 and 2 (2 out of 3 cases) and both behaved in a thyroiditis fashion." (PMID 16219106, 2005). "Thyroid peroxidase mRNA expression in peripheral blood was detected in significantly more number of patients with thyroid disease than in control patients." (PMID 15213710, 2004). "Studies have demonstrated that specific strains of Bifidobacterium and Lactobacillus are pathogenic due to structural homology with the amino acid sequences of human TPO and Tg and thus can induce autoimmunity thyroid diseases through a cross-antigen-molecular mimicry mechanism." (PMID 40642174, 2025). "Serum levels of thyroid-stimulating hormone (TSH), free thyroxine (fT4), free triiodothyronine (fT3), and thyroid antibodies (anti-thyroid peroxidase antibodies (aTPO), anti-thyroglobulin antibodies (aTG)) were measured, and muscle strength was assessed using hand-held dynamometry." (PMID 40332280, 2025). "The present study demonstrated that thyroid dysfunction, predominantly subclinical hypothyroidism, was present in 11.4% of women with GDM and was significantly associated with advancing maternal age, higher body mass index, family history of thyroid disorder, and anti-TPO antibody positivity." (PMID 41473631, 2025). "Third, excluding participants with a family history of thyroid disease may have led to an underestimation of the true prevalence of TPO-Ab." (PMID 40927297, 2025). "Thyroid peroxidase (TPO) antibodies were within normal limits (titers too low to detect), suggesting no underlying thyroid autoimmune pathology." (PMID 41246727, 2025).
thyroid (continued). "In HT, the immune system mounts an autoimmune response against thyroid antigens, leading to chronic inflammation, predominantly mediated by autoreactive T lymphocytes and the production of anti-thyroid peroxidase (anti-TPO) and anti-thyroglobulin (anti-TG) antibodies." (PMID 40722630, 2025). "Besides modified TFTs, the presence of thyroid peroxidase (TPO) antibodies was used to assess thyroiditis." (PMID 40227797, 2025). "The American Thyroid Association (ATA) and the Endocrine Society recommend the screening of thyroid disease in women with morbid obesity (BMI ≥ 40 kg/m2), TPO positivity, family or personal history of thyroid disease, and age >30 years, before and after pregnancy." (PMID 39345886, 2024). "As for thyroid antibodies, 4/10 cases had elevated antibodies with three of them being anti-TPO." (PMID 39021640, 2024). "In AITD, thyroid peroxidase (TPO) and thyroglobulin (Tg) antibodies may also cross the placenta, potentially interfering with maternal and fetal thyroid function." (PMID 39434884, 2024). "In fact, the presence of Anti-thyroglobulin (TG) and/or anti-thyroid peroxidase (TPO) autoAbs increase the risk of ICI-induced thyroid dysfunction; the presence of anti-thyroid autoAbs has been described in 13–70% of patients who develop ICI-associated thyroid dysfunction." (PMID 38611115, 2024). "We present current evidence from cross-sectional studies in several disparate populations of the possible short-term modulation of thyroid autoimmune markers, thyroid peroxidase (TPOAb) and thyroglobulin antibodies (TgAb), with minimal disruption of biochemical thyroid function." (PMID 39770919, 2024). "A prospective study that aimed to compare the incidence of thyroid diseases over six years found a significant increase in subclinical hypothyroidism, TPO, and thyroglobulin antibody (Tg Ab) positivity, and thyroid ultrasound hypo-echogenicity among psoriatic arthritis patients, particularly women." (PMID 39337081, 2024). "It is unknown whether a subset of patients with autoantibodies present early in the course of disease will go on to develop CTD autoantibody–associated clinical manifestations such as myositis (e.g., anti-SRP54) or thyroiditis (anti-TPO)." (PMID 36752204, 2023). "Few types of studies have used Anti-TPO as a biomarker for identifying autoimmune thyroid disease in Nepal, which limits the amount of research that has been done on the autoimmune profile in thyroid disease." (PMID 37821852, 2023). "The major thyroid autoantigens are thyroglobulin, thyroid stimulating hormone receptor and TPO." (PMID 38013274, 2023). "As the endogenous corticosteroid cortisol exhibits immunosuppressive qualities, its rapid decrease in the postpartum period may account for a flare-up of thyroid symptoms in TPO-positive women." (PMID 37868409, 2023). "High anti-TPO antibody positivity status in the reproductive age group in our study could also support the essence of universal thyroid screening for pregnant females and newborns." (PMID 37821852, 2023). "Other studies indicate that as many as 80% of women with positive TPO antibodies in the third trimester may subsequently develop postpartum thyroiditis." (PMID 37868409, 2023). "Moreover, we observed in CTD patients a prevalence of 24% of thyroiditis, although in another study the overall prevalence of either anti-TPO or anti-TG detection was up to 62.3% among CTD patients while it was 8% among controls." (PMID 35222042, 2022). "TC, gender, TPO-Ab, Tg-Ab, CR, and TG all have involvement in thyroid diseases." (PMID 35282438, 2022). "TKI-induced thyroid alterations are caused by several direct mechanisms, such as thyroid damage ranging from mild follicular cells toxicity to destructive thyroiditis, inhibition of thyroid peroxidase, blocking iodine uptake, and increased thyroid hormone clearance." (PMID 34283388, 2022).